CCL11 (C-C motif chemokine ligand 11)
Diseases named in the same sentence as CCL11 in open-access papers (continued):
Sharing a sentence is not in itself a finding about the gene and the disease.
asthma (continued). "Therefore, the selective blockade of the CCR3-eotaxin-1/CCL11 axis could impair eosinophil recruitment, representing an attractive target for the treatment of asthma, allergic rhinitis, and other eosinophil-related conditions." (PMID 29962972, 2018). "Thus, decreased plasma CCL11 level might be regulated by IL-17 overexpression in mild to moderate adult asthma." (PMID 29138487, 2017). "Galectin-9 has demonstrated efficacy in a Dermatophagoides farinae allergen-induced asthma model by suppressing the expression of IL5, IL13, CCL11, CCL17, reducing eosinophilia, and pulmonary hyperresponsiveness." (PMID 41516283, 2025). "Here we demonstrated that SR1001 prevents CCL11/CCR3-induced ERK phosphorylation in eosinophils, possibly by increasing BMAL1 and thereby impeding this crucial pathomechanism of asthma." (PMID 40131242, 2025). "Specific chemokines, such as CCL11, CCL5, and CXCL12, have been shown to play critical roles in airway inflammation in asthma by promoting the migration and activation of eosinophils and DCs, thereby driving excessive inflammatory responses in the airways." (PMID 41036310, 2025). "Recently, it was demonstrated that mainly IL-13 induces CCL11 and CCL24 in fibroblasts and monocytes, which was required for eosinophil attraction in HDM-induced murine asthma." (PMID 40276331, 2025). "Initially described by P.J. Jose in 1994 during experiments on asthma, CCL11(eotaxin-1) was demonstrated as a potent chemokine that promotes migration andactivation of eosinophils participating in the pathogenesis of a broad range ofallergy-related diseases." (PMID 40026499, 2025). "Corni Fructus has been reported to reduce IL-5, CCL11, and OVA-specific IgE and inhibit eosinophil infiltration in the OVA-induced asthma model." (PMID 35887796, 2022). "CCR3 is one of the most relevant chemokine receptors in asthma, and its ligands are CCL3, CCL5, CCL11, and CCL13." (PMID 35743888, 2022). "The IL-4/IL-13/STAT6 pathway induces expression of inflammatory chemokines such as CCL11, CXCL1, and CXCL3 and is a central pathway in the pathophysiology of asthma, especially airway hyperresponsiveness." (PMID 35281012, 2022). "It was already reported that this key cell of the allergic response during asthma, the eosinophil, is activated by cytokines (IL-5) and chemokines (CCL5, CCL11) via the activation of MSK1." (PMID 33450992, 2021). "We made the observation that GC insensitivity present in ASM cells derived from severe asthma was also reported to be gene-specific with CCL5, IL-6 and CCL11 being resistant to dexamethasone (or fluticasone), while CXCL10 still being repressed by either GCs." (PMID 35387008, 2021). "Eotaxin-1 (CCL11) is a potent and eosinophil-specific chemoattractant, and it is involved in eliciting inflammation and allergic reactions, as well as asthma." (PMID 34206780, 2021). "Eotaxin-1 (CCL11) is an important chemokine for eosinophilic recruitment and the progression of asthma." (PMID 33471779, 2021). "Eotaxin-1/CCL11 is primarily involved in recruitment of eosinophils into inflammatory sites and plays a role during allergy-related diseases such as asthma and allergic rhinitis as well as inflammatory disorders such as atherosclerosis." (PMID 32147601, 2020). "This is in line with the assumption that IL-5 and CCL-11/eotaxin-1 together with others TH2 cytokines play critical roles in orchestrating and amplifying allergic inflammation in asthma." (PMID 29849493, 2018). "Most studies on CCL11 are associated with allergy and asthma because this chemokine has been identified as a potential biomarker for the diagnosis and assessment of asthma severity and control but there are no studies on the role of CCL11 in addictive disorders." (PMID 28149283, 2016). "Active eosinophils recruitment is predominantly exerted by proteins secreted by epithelia, the most potent chemoattractant for these cells being eotaxin-1 (CCL11), that account for 80 % of TGF-ß expression in asthma." (PMID 26430389, 2015).
asthma (continued). "Given that CCL11 plays an important role in eosinophil chemotaxis in asthma, we also examined the effect of GSNOR inhibitor on airway CCL11 production." (PMID 23936192, 2013). "Moreover, CCL11 is important in promoting IL-13-associated allergic lung responses since mice deficient in both IL-5 and CCL11 have an intrinsic defect in IL-13 production by T cells and an impaired development of lung eosinophilia and AHR in experimental asthma." (PMID 23936192, 2013). "Conversely, treatment of established asthma with rapamycin increased both the number of BALF inflammatory cells, as well as lung mRNA levels of the C-C chemokine, CCL11." (PMID 22685525, 2012). "We found that the following chemokines were significantly up-regulated in the serum in asthma compared to healthy subjects CCL2, CCL4, CCL11 and CCL13 (p < 0.05)." (PMID 19602238, 2009). "Eotaxin (chemokine C-C motif ligand 11 (CCL11)), a member of the CC chemokine family, recruits eosinophils to sites of inflammation, particularly in allergic diseases and asthma." (PMID 18312691, 2008). "Interestingly, there are reports that eosinophils isolated from patients with asthma produce more EVs than healthy subjects, and that eosinophils exposed to the eosinophil activators, CCL11 (eotaxin-1) and TNF, secrete more EVs." (PMID 41214609, 2025). "Regarding the role of CCL11 in inducing premature aging within the context of asthma, we have shown a decrease in telomere length in peripheral blood mononuclear cells (PBMC) accompanied by an increased expression of eotaxin-1/CCL11 in plasma samples from severe asthma patients." (PMID 37860000, 2023). "Furthermore, local expression of the chemokines CCL-11 (eotaxin-1) and CCL-26 (eotaxin-3) is increased in asthma and allergic rhinitis." (PMID 36679633, 2023). "We examined serum chemokine (CCL4, CCL11, CCL26, and CCL17) and total IgE serum levels, fractionated exhaled nitrogen oxide (FENO), and CCL4 expression in nasal polyps in patients with severe ECRS and asthma." (PMID 35892679, 2022). "In the study on treatment of asthma, it can diminish the expression of IL-4, IL-5, IL-13, IL-17A, IgE, CCL5, and CCL11, inhibit NF-kB- and JNK-mediated inflammatory signaling, and reduce oxidative damage through decreasing the activity of ROS and increasing SOD." (PMID 36588723, 2022). "Since TNF induces pentraxin-3 secretion and the later promotes the secretion of eotaxin-1/CCL11, it is legitimate to speculate that pentraxin-3, in an autocrine manner, mediates some of the effects of TNF in asthma." (PMID 35387000, 2021). "On the other hand, IL-37 not only targets TSLP through NF-κB and ERK1/2 signaling pathways, but also may act on tracheobronchial epithelial cells to inhibit fibroblasts and AMSC from producing CCL11, thereby alleviating house dust mite(HDM)-induced asthma." (PMID 34248996, 2021). "It is known that CCL5, CCL11, and CCL24 may contribute to the airway recruitment of fibrocytes in severe asthma." (PMID 31548841, 2019). "It is well known that eosinophils that respond to a variety of CC chemokines, such as CCL11 (eotaxin), CCL24 (eotaxin-2) and CCL26 (eotaxin-3), are proinflammatory granulocytes with significant roles in several inflammatory diseases, including asthma." (PMID 27304950, 2016). "A recent work evaluated CCL11 levels in bronchoalveolar lavage fluid (BALF), exhaled breath condensate (EBC), blood and sputum and evidenced a correlation between this protein in induced sputum and asthma severity." (PMID 26430389, 2015). "In this paper we describe how ASMC-derived CXCL10, CCL11, or RANTES may contribute to airway inflammation in asthma and how these chemokines can be controlled by the anti-inflammatory action of DMF." (PMID 23606796, 2013).
asthma (continued). "Particularly, epithelial STAT3 was identified as a critical regulator of allergen-induced inflammation and AHR in a murine model of asthma, IL-17A-induced STAT3 activation led to CCL11/eotaxin-1 production in HASM, and PDGF-induced STAT3 mediated the proliferation in HASM cells." (PMID 24499258, 2013). "CXCL10, CCL11, and RANTES derived from ASMC are believed to be crucially involved in chemotaxis of immune cells into the asthmatic airways and are therefore actively involved in the development of airway inflammation in asthma." (PMID 23606796, 2013). "ASMCs of asthma patients secrete proinflammatory chemokines CXCL10, CCL11, and RANTES which attract immune cells into the airways and may thereby initiate inflammation." (PMID 23606796, 2013). "Rapamycin treatment of established asthma, however, increased mRNA levels of CCL11 and did not affect the expression of CCL7 or CCL24." (PMID 22685525, 2012). "However, recombinant and ASM-derived CCL11 was inactivated by β-tryptase and co-culture with mast cells and as mast cells are located within the ASM bundle in asthma this questions the importance of ASM CCR3 activation in disease." (PMID 19735481, 2009). "Hence, it is plausible that PTX3-mediated eotaxin-1/CCL11 release may down-regulate exaggerated neutrophilic inflammation, via the suppression of CXC chemokine, especially in the context of severe asthma." (PMID 31437159, 2019). "In the present study, we also investigated the chemokine ligand levels, that is, CCL11 (also known as eotaxin), and CCL24 (also known as eotaxin-2 or myeloid progenitor inhibitor factor-2), which are all epithelial cell–derived chemokines involved in the pathogenesis of asthma and rhinitis." (PMID 31548841, 2019). "ASMCs from patients with asthma are in a hyperproliferative phase, overexpress the chemokines chemokine (C–C motif) ligand (CCL) 11 (CCL11) and CXCL8, and particularly in patients with severe asthma, there is a reduced effect of corticosteroids in inhibiting TNFα-induced release of CCL11 and CXCL8." (PMID 28842514, 2017). "In addition to CCL11/eotaixn-1 and TNF-alpha, HBEC exposed to TSLP induced the secretion of CCL22/MDC and CCL17/TARC, two CCR4-ligands that are considered critical Th2-related chemokines in asthma exacerbations." (PMID 25546419, 2014). "Interestingly, we report the discovery that NRF2 activation by KEAP1 knockdown or by pharmacological activators of NRF2 can specifically inhibit Eotaxin-1/CCL11 expression in human lung fibroblasts independent of several other chemokines further implicating this pathway in asthma pathogenesis." (PMID 23061798, 2012). "On the contrary, CPX increased the expression of MHCII, CD40L, Il-13, eotaxin (Ccl11), Mbp, and Epo on late reaction; therefore, CPX did not significantly decrease the entire asthma pathway." (PMID 36934237, 2023). "Although TSLP and CCL11/eotaxin-1 play a critical role in the pathogenesis of asthma, it is noteworthy that TSLP alone was not enough to induce CCL11/eotaxin-1 in control HBEC." (PMID 25546419, 2014). "Furthermore, we have previously demonstrated that CCL11 (Eotaxin), is not only released in higher concentrations from ASM cells of patients with asthma compared to nonasthmatic control subjects, but also that dexamethasone can’t repress this release effectively in asthmatic patients." (PMID 24886442, 2014).
eosinophilia (61 papers, 2007 to 2025). "The characteristic Th2-related cytokines (Il4, Il5, Il13) were markedly increased in AD-like lesions, while Il4 and Ccl11 expression was elevated to various extent in PN-like lesions appeared to be associated with dermal eosinophilia." (PMID 41229431, 2025). "Indeed, the depletion or deficiency of IL-5 or CCL11 or blockade of IL-5R abrogates eosinophilia in several helminth infections." (PMID 33042162, 2020). "This was evidenced by elevated levels of IL-5, IL-13, and CCL11; enhanced eosinophilia; and higher numbers of total cells, lymphocytes, macrophages, and neutrophils in the BALF." (PMID 40587812, 2025). "Of note, peak CCL11 concentrations preceded the peak lung eosinophilia, observed at 7–10 DPC, by several days in the breakthrough infection mice." (PMID 41190814, 2025). "Insofar as eotaxin-1 (CCL-11) is an eosinophil chemoattractant, and as tumor-associated tissue eosinophilia is linked with improved CRC prognosis, heightened Eotaxin-1 in CRC was confirmed here and elsewhere." (PMID 38954024, 2024). "Inflammation with eosinophilia is regulated by the chemokines CCL11 and the cytokines IL-13, IL-5, and IL-33." (PMID 36970065, 2023). "IL-5 promotes eosinophilia, and IL-4 and IL-13 enhance the production of eosinophil chemoattractants (CCL11/eotaxin-1, CCL24/eotaxin-2, and CCL26/eotaxin-3) and activate B cells, macrophages, fibroblasts, epithelial cells, and goblet cells." (PMID 37674852, 2023). "Lysophosphatidylcholine participates in the recruitment of eosinophils IL-5 and IL-3 stimulate eosinophilia, and recruitment is mediated mainly by chemoattractant CCL11 and CCL26 (eotaxins)." (PMID 33732246, 2021). "Nevertheless, our results are consistent with the findings of that the comparable level of CCL11, but reduced eosinophilia, was detected with lower eATP levels." (PMID 34201190, 2021). "Eotaxin-1 (CCL11), a potent eosinophil chemoattractant that is considered a major contributor to tissue eosinophilia, is a key regulator of intestinal inflammation and seems to be involved both in UC and CD." (PMID 30417021, 2018). "After demonstrating MBP, CCL5 and CCL11 in tissues of affected organs and presence of eosinophilia, we next evaluated levels of these and other eosinophilic granules and chemokines in sera." (PMID 28489854, 2017). "The observation that CCL11 is highly expressed in the gut of very young neonates is consistent with mucosal eosinophilia." (PMID 28619048, 2017). "It is possible that the increased expression of CCL11 induced by the present dsRNA-induced exacerbation contributed to the increased BALF eosinophilia." (PMID 26879906, 2016). "We first performed a concentration-response experiment with HDM extract with a standard sensitization protocol to determine the amount of HDM extract (6.25 μg), which elicited minimal BHR, eosinophilia, and Ccl11 and Muc5ac mRNA in WT mice." (PMID 27489884, 2016). "On the other side, depletion of macrophages before allergen/rhinovirus challenge lead to reduced eosinophilia, CCL11 and IL-13 levels." (PMID 24612750, 2014). "Cutaneous eosinophilia persisted in Sharpin−/−, Il4ra−/− mice, although expression of Il5 mRNA was reduced and the expression of Ccl11 and Ccl24 was completely abolished." (PMID 24465642, 2014). "Tissue eosinophilia during the allergic process is mainly coordinated by interleukin (IL)-5 and the CC chemokine CCL11/eotaxin both in experimental animals and human subjects." (PMID 23316161, 2012). "The induction of eosinophilia during T. muris infection is under the control of IL-5 and the chemokine CCL11 which work in synergy to recruit eosinophils." (PMID 23053395, 2012). "The same treatment also significantly reduced the expression of genes linked to Th2 response and eosinophilia (Il4 and Il5 but not Il13) as well as eosinophil recruitment (Ccl5 and Ccl11) in Atg7fl/fl;Lyz2‐Cre ECRS mice." (PMID 35988262, 2022).
eosinophilia (continued). "Besides, CCL11 is highly expressed in active CD, contributes to tissue eosinophilia, and regulates intestinal inflammation." (PMID 34469062, 2021). "For instance, CCL11 mediated eosinophilia which may be key in host defense against Na is also a hallmark of Pf infection." (PMID 33604551, 2019). "Therefore, the effect of IFN-β on CCL11 production was evaluated in NP-derived stromal cells to verify the role of IFN-β in nasal tissue eosinophilia." (PMID 30455684, 2018). "IL-5 and CCL11 cooperate to generate an intestinal eosinophilia in a model of gastrointestinal allergy; here, initial eosinophil release from the bone marrow appears to be mediated by IL-5, whereas local production of CCL11 in the intestine mediates the recruitment from the blood to the intestine." (PMID 21155838, 2011). "OVA inhalation significantly upregulated both CCL11 and CCL24 expression in the lungs of neonatally OVA-exposed mice, compatible with the presence of BALF eosinophilia." (PMID 34207237, 2021). "Intratracheal administration of LY294002 reduced OVA-induced increases in total cell counts, eosinophil counts, and IL-5, IL-13, and CCL11 (eotaxin) levels in BAL fluid and dramatically inhibited OVA-induced tissue eosinophilia and airway mucus production." (PMID 23690670, 2013). "CCL11 KO mice have reduced numbers of these cells in the colon and double knockout mice of CXCL11 and IL-5 completely lack eosinophilia." (PMID 23053395, 2012). "Similarly, CCL11 concentrations were highest in the breakthrough infection mice only at 1 DPC, much earlier than peak lung eosinophilia at 7-10 DPC." (PMID 41190814, 2025). "Also, the analyses of post-mortem RNA-sequencing with COVID-19-infected lungs versus normal controls show the significant expression and upregulation of genes related to eosinophilia, such as CLC (Galectin-10), RNASE2 (EDN), and CCL11 (eotaxin-1)." (PMID 40710346, 2025). "The expression of CCL11, CCL24, and IL33 increased significantly in mice treated with PPE alone, which may contribute to PPE-induced eosinophilia in the lung." (PMID 34950055, 2021). "It is worth noticing that despite the baseline eosinophilia, eosinophil chemo-attractants CCL11 and CCL5 did not correlate with eosinophil count and their concentration was either unaltered (CCL11) or decreased (CCL5) in S. stercoralis-infected subjects." (PMID 33059754, 2020). "The underlying mechanism for this effect is unclear, as the reduction in eosinophilia was not correlated with a decrease in IL-5, CCL11, or CCL24, and eosinophil migration itself was not inhibited by IL-2c." (PMID 29196657, 2017). "We further demonstrate a degree of selectivity in the steroid action in that tissue CCL5 expression, but not CCL11, is reduced by budesonide along with its attenuating effects on tissue eosinophilia." (PMID 20459697, 2010). "We have focused on epithelial and subepithelial eosinophilia, expression of CCL11 and CCL5, and occurrence of apoptotic and non-apoptotic eosinophils in the human nasal mucosa with resolving tissue eosinophilia." (PMID 20459697, 2010). "Interestingly, CCL11 (Eotaxin-1) did not appear to have a strong signal at the acute time points when peak lung eosinophilia was observed in OVA-sensitized mice." (PMID 41190814, 2025). "Since no major CCL11 or IL-5 signature was observed in TIV-vaccinated NC99-challenged mice, we may be observing CCL5-mediated recruitment of eosinophils instead of canonical Type 2 cytokine-driven eosinophilia." (PMID 37600776, 2023).